PHLPP2 (PH domain and leucine rich repeat protein phosphatase 2)
Diseases named in the same sentence as PHLPP2 in open-access papers (continued):
Sharing a sentence is not in itself a finding about the gene and the disease.
Hepatic steatosis (3 papers, 2016 to 2025). Steatosis is a term used to denote lipid accumulation within hepatocytes. "For PHLPP2, maintaining balanced PHLPP2 expression levels is critical for disease prevention, as changes in steady-state levels of PHLPP2 are associated with many diseases, including diabetes, hepatic steatosis, and cancer." (PMID 36101384, 2022). "In another context, KCTD17 binds to phosphorylated PHLPP2, targeting it for ubiquitin‐mediated degradation, thereby promoting hepatic steatosis." (PMID 41000374, 2025). "Commensurately, forced PHLPP2 expression ameliorates hepatic steatosis in diet-induced obese mice." (PMID 26743335, 2016).
hypopharyngeal squamous cell carcinoma (3 papers, 2015 to 2019). "It is necessary to investigate the expression patterns of PHLPP1 and PHLPP2 in hypopharyngeal squamous cell carcinomas (HSCCs) and clarify their clinical significance." (PMID 25793736, 2015). "Moreover, low expression of PHLPP2 was significantly related to the advanced tumor stage, poor differentiation, and increased lymph node metastasis in patients with hypopharyngeal squamous cell carcinoma." (PMID 29209625, 2017).
Insulin resistance (3 papers, 2018 to 2022). Increased resistance towards insulin, that is, diminished effectiveness of insulin in reducing blood glucose levels. "In conclusion, for the first time, this study provides evidence that an essential link exists between miR-214 and insulin resistance and between miR-214-dependent insulin resistance and PHLPP2 in endothelial cells." (PMID 29425121, 2018). "In conclusion, this study shows that PHLPP2 is a target of miR-214 in MAECs, and identifies miR-214 downregulation as a contributing factor to MGO-induced endothelial insulin-resistance." (PMID 29425121, 2018). "In the present study, we report differential increase in expression of both PHLPP1 and PHLPP2, in hyperinsulinemia mediated insulin resistance in two neuronal cell lines in vitro, with or without insulin stimulation." (PMID 36376971, 2022). "However, insulin resistance upregulated expression of PHLPP1 by 4.2 fold (lane 1 vs. lane 3) and of PHLPP2 by 2.3 fold (lane 1 vs. lane 3) irrespective of insulin stimulation." (PMID 36376971, 2022).
keloid (3 papers, 2017 to 2025). An irregularly shaped, elevated mark on the skin caused by deposits of excessive amounts of collagen during wound healing. "MiR-181a promotes keloid fibroblast proliferation and survival by directly targeting PHLPP2, a negative regulator of AKT signaling." (PMID 41424791, 2025). "Its overexpression suppresses PHLPP2, leading to enhanced AKT activation, increased DNA synthesis, and reduced apoptosis, highlighting the miR-181a/PHLPP2/AKT axis as a key driver of keloid fibroblast hyperproliferation." (PMID 41424791, 2025). "miRNA-21, miRNA-181a were up-regulated in keloid and these miRNAs may negatively regulate PTEN and PHLPP2 expression at the post-transcriptional level." (PMID 29088812, 2017).
non-small cell lung carcinoma (3 papers, 2015 to 2021). A group of at least three distinct histological types of lung cancer, including non-small cell squamous cell carcinoma, adenocarcinoma, and large cell carcinoma. "It has been reported PHLPP2 is downregulated by miR-205 and leads to stimulation of proliferation and angiogenesis in non-small cell lung cancer cells." (PMID 25888950, 2015). "MiR-141-3p was reported to promote proliferation of non-small cell lung cancer cells by PH domain leucine-rich-repeats protein phosphatase 1 (PHLPP1) and PHLPP2." (PMID 26569605, 2015).
bladder urothelial carcinoma (2 papers, 2019 to 2021). "Consistent with previous findings for bladder urothelial carcinoma, breast invasive carcinoma, colon adenocarcinoma and prostate adenocarcinoma, PHLPP2 levels were significantly lower in the tumor tissues than those in non‐tumor tissues." (PMID 31571378, 2019).
Cerebral ischemia (2 papers, 2019 to 2022). Restriction of arterial blood supply to the brain associated with insufficient oxygenation to support the metabolic requirements of the tissue. "PHLPP2 similarly promotes neuronal death and siRNA mediated gene knockdown decreased brain damage in a rat model of global cerebral ischemia." (PMID 36291561, 2022). "PHLPP2 inhibition leads to neuronal protection after cerebral ischemia/reperfusion injury in rats." (PMID 30678657, 2019).
colorectal adenocarcinoma (2 papers, 2021 to 2022). The most common type of colorectal carcinoma. "In an attempt to determine how PHLPP phosphatases regulate lumenogenesis, we first tested the effects of depleting PHLPP1 and PHLPP2 expression in Caco-2 colorectal adenocarcinoma cells." (PMID 35997536, 2022).
colorectal tumor (2 papers, 2021 to 2022). "Furthermore, in contrast to miR-509-3p, PHLPP2 was found to be significantly downregulated within the colorectal tumor tissues as compared to the adjacent normal (median: − 8.984 (tumor) vs. -5.611 (NAT); N = 25; p < 0.0001)." (PMID 35361144, 2022). "By hierarchical clustering of hub genes using Xena Functional Genomics Explorer, we found that PHLPP2, ACALB, IGF1, and BCL2 were low‐expressed in colorectal tumor tissues." (PMID 33190424, 2021).
Hyperglycemia (2 papers, 2022 to 2025). An increased concentration of glucose in the blood. "In hyperglycemia conditions, the downregulation of BMI1 expression caused a significant increase in PHLPP1 and PHLPP2 in both cell lines." (PMID 36497428, 2022). "The analysis of PHLPP phosphatases mRNA expression showed that prolonged insulin stimulation of HEC-1A cells caused both in hypoglycemia and hyperglycemia conditions to a decrease in PHLPP1 and increase in PHLPP2 after 4 h stimulation and then the level was similar to in control cells." (PMID 36497428, 2022). "This suppression may result from multiple mechanisms: hyperglycemia-induced disruption of the liver kinase B1 (LKB1) complex, activation of protein phosphatase PP2A, upregulation of PH domain and leucine-rich repeat protein phosphatase 2 (PHLPP2), and ubiquitin-mediated degradation of AMPK subunits." (PMID 40647154, 2025).
pancreatic ductal adenocarcinoma (2 papers, 2019 to 2023). An infiltrating adenocarcinoma that arises from the epithelial cells of the pancreas. "Targeting PHLPP2 specifically could reduce its expression, thereby inhibiting the occurrence and proliferation of tumor cells in pancreatic ductal adenocarcinoma." (PMID 31757221, 2019). "Another study reported that the upregulation of METTL3 caused an increase in miR-25-3p and that miR-25-3p could promote the expression of its target protein PHLPP2 to promote pancreatic ductal adenocarcinoma occurrence." (PMID 31757221, 2019). "Ultimately, the study revealed that the METTL3-miR-25-3p-PHLPP2-AKT regulatory axis might influence the transformation of pancreatic ductal adenocarcinoma induced by cigarette smoking." (PMID 31757221, 2019).
acute kidney injury (1 paper, 2019). Sudden and sustained deterioration of the kidney function characterized by decreased glomerular filtration rate, increased serum creatinine or oliguria. "rs78064607, the only SNP with genome-wide significance in our study is located in PHLPP2 (PH Domain and Leucine Rich Repeat Protein Phosphatase 2) and was associated with increased risk of acute kidney injury." (PMID 30678657, 2019). "We identified several potential loci, in particular PHLPP2, BBS9, RyR2, DUSP4 and HSPA8, associated with new-onset of atrial fibrillation, delirium, myocardial infarction, acute kidney injury and stroke after cardiac surgery." (PMID 30678657, 2019).
acute myeloid leukemia (1 paper, 2020). Acute myeloid leukemia (AML) is a group of neoplasms arising from precursor cells committed to the myeloid cell-line differentiation. "More recent studies demonstrated the anti-proliferative potential of C/EBPs through their repression of a cluster of microRNAs that induce the expression of the tumor suppressor phosphatase PH domain and leucine rich repeat protein phosphatase 2 (PHLPP2) in acute myeloid leukemia (AML) cells." (PMID 32674309, 2020).
alcoholism (1 paper, 2018). "And as such we speculate that the effect may be implemented by the OMRGs, including PHLPP2 and EGF, as well as three pathways (alcoholism, systemic lupus erythematosus, and proteoglycans in cancer) through which the OMRGs may be response to OM." (PMID 29887852, 2018).
Autoimmunity (1 paper, 2017). The occurrence of an immune reaction against the organism's own cells or tissues. "Larger patient groups are required to determine whether a loss-of-function polymorphism in PHLPP2 might contribute to the susceptibility of autoimmunity." (PMID 27477328, 2017).
brain tumors (1 paper, 2015). "To investigate the composition of NHERF1 protein complexes in ependymoma, we screened the intracellular localization of the NHERF1 ligands moesin, NF2, PTEN, PDGFRα, EGFR, YAP1, β-catenin and PHLPP2 that have been functionally involved in primary brain tumors." (PMID 25775275, 2015).
cardiac hypertrophy (1 paper, 2022). "Taken together, we report that METTL14 regulates Akt signaling by altering m6A modification of Phlpp2 mRNA in cardiomyocytes, revealing a possible molecular mechanism underlying the role of RNA m6A modification in exercise-induced physiological cardiac hypertrophy." (PMID 36351918, 2022).
endometrial tumors (1 paper, 2021). "In endometrial tumors, m6A methylation of the AKT negative regulator PHLPP2 can facilitate YTHDF1-mediated translation of the PHLPP2 gene, inhibiting the AKT signaling pathway and leading to attenuated cell proliferation, migration and invasion." (PMID 33758623, 2021).
esophageal cancer (1 paper, 2015). A primary or metastatic malignant neoplasm involving the esophagus. "However, our current study is limited to proof-of-principle and further investigations are needed to understand the role of miR-224 in esophageal cancer and clarify how miR-224 regulates expression of PHLPP1 and PHLPP2 proteins during esophageal cancer compared to other cancer pathogenesis." (PMID 26245343, 2015).
esophageal squamous cell carcinoma (1 paper, 2025). Esophageal squamous cell carcinoma (ESCC) is a type of esophageal carcinoma (EC) that can affect any part of the esophagus, but is usually located in the upper or middle third. "Moreover, RNF149 confers cisplatin resistance in esophageal squamous cell carcinoma through PHLPP2 ubiquitination." (PMID 41000374, 2025).
head and neck squamous cell carcinoma (1 paper, 2024). A squamous cell carcinoma that arises from any of the following anatomic sites: lip and oral cavity, nasal cavity, paranasal sinuses, pharynx, larynx, and salivary glands. "Through modifying PHLPP2 and FOXO4, miR-762 expression may stimulate the AKT signalling pathway in head and neck squamous cell carcinoma and promote migration, proliferation, and EMT17." (PMID 38589525, 2024).
Hypoglycemia (1 paper, 2022). A decreased concentration of glucose in the blood. "In Ishikawa cells, insulin stimulation causes PHLPP1 and PHLPP2 to increase in hypoglycemia conditions and this effect is enhanced by PTC-209 treatment." (PMID 36497428, 2022).
leukemia (1 paper, 2021). A malignant (clonal) hematologic disorder, involving hematopoietic stem cells and characterized by the presence of primitive or atypical myeloid or lymphoid cells in the bone marrow and the blood. "Silencing PHLPP2 protein expression prolongs the survival of leukemia cells subjected to severe glucose limitation by promoting a switch to AMPK-mediated fatty acid oxidation for energy generation." (PMID 34608126, 2021). "Thus, regulation of AMPKα phosphorylation and cell viability in human leukemia cells under glucose stress is unique to PHLPP2." (PMID 34608126, 2021). "PHLPP2 and pAMPK interact with each other, and the pleckstrin homology (PH) domain on PHLPP2 is required for their interaction, for dephosphorylating and inactivating AMPK, and for the apoptotic response of the leukemia cells to glucose limitation." (PMID 34608126, 2021). "Our studies show that in glucose-deprived T leukemia cells, activated PHLPP2 targets AMPK, rather than Akt or S6K." (PMID 34608126, 2021).
liver fibrosis (1 paper, 2023). "Studies have shown that hyperoside has an anti-inflammatory and antioxidant profile that may help to protect the liver from damage and slow the progression of liver fibrosis, by suppressing canonical NF-κB signaling, via upregulation of Nrf2, or via the PHLPP2-AKT-GSK-3β signaling pathway." (PMID 37371866, 2023).
lymph node metastasis (1 paper, 2019). "The low PHLPP2 expression level was found to be associated with the presence of lymph node metastasis (P = 0.003)." (PMID 31571378, 2019). "Low PHLPP2 expression was found to be significantly correlated with the presence of lymph node metastasis (P = 0.003)." (PMID 31571378, 2019).
mantle cell lymphoma (1 paper, 2013). Mantle cell lymphoma is a rare form of malignant non-Hodgkin lymphoma affecting B lymphocytes in the lymph nodes in a region called the ``mantle zone''. "In mantle cell lymphoma (MCL), the protein phosphatase PHLPP2, an important negative regulator of the PI3K/AKT pathway, was identified as an additional important target of miR-17-92 miRNAs." (PMID 24145746, 2013).
neuroblastoma (1 paper, 2022). Neuroblastoma (NB) is the most common solid, extracranial childhood tumor. "We observed elevated expression of both PHLPP1 and PHLPP2 in insulin resistant neuronal cells (Neuro-2A, mouse neuroblastoma; SHSY-5Y, human neuroblastoma) as well as in the whole brain lysates of high-fat-diet mediated diabetic mice." (PMID 36376971, 2022).
nonalcoholic steatohepatitis (1 paper, 2023). "KCTD17 expression is increased in the livers of obese mice and patients with NAFLD/nonalcoholic steatohepatitis (NASH), leading to the degradation of pleckstrin homology domain leucine-rich repeat protein phosphatase 2 (PHLPP2) to prolong insulin signaling by dephosphorylating AKT97." (PMID 37779139, 2023).
oral squamous cell carcinoma (1 paper, 2025). "Similarly, MARCH1 promotes oral squamous cell carcinoma growth via PHLPP2 ubiquitination." (PMID 41000374, 2025).
pancreatic adenocarcinoma (1 paper, 2023). "Based on the OncoLnc database, we found the high expression of PHLPP2 was correlated with higher survival percent of patients with brain lower-grade glioma (LGG; logrank P = .00623) and pancreatic adenocarcinoma (PAAD; logrank P = .00109)." (PMID 37737218, 2023).
prostate tumor (1 paper, 2020).
squamous cell carcinoma (1 paper, 2019). A carcinoma arising from squamous epithelial cells. "PHLPP2 expression was then examined by immunohistochemistry, and its clinical significance analyzed in 134 NSCLC patients, including 73 patients with adenocarcinoma and 81 with squamous cell carcinoma." (PMID 31571378, 2019).
steatosis (1 paper, 2016). Increased lipid within the cytoplasm of cells. "To test whether reduction in hepatic PHLPP2 is sufficient to induce steatosis, we constructed adenoviruses encoding shRNA targeting either Phlpp1 (Ad-shPHLPP1) or Phlpp2 (Ad-shPHLPP2)." (PMID 26743335, 2016).
thyroid carcinoma (1 paper, 2019). "We also found that PHLPP2 expression is deregulated in kidney renal clear cell carcinoma and thyroid carcinoma." (PMID 31571378, 2019).
tumor (56 papers, 2010 to 2026). "Similar results were obtained in a second example in patient CRC1 for PHLPP2-specific TCRs confirming the association between structural avidity and tumor residence." (PMID 37280206, 2023). "We identified that the PHLPP2 gene was downregulated in the READ tumor samples compared with control, and the downregulation of PHLPP2 was associated with a poor prognosis." (PMID 37737218, 2023). "Overexpression of PHLPP2 or its isoform is associated with a decreased cell proliferation and tumor development in vitro and in animal models." (PMID 35361144, 2022). "Overexpression of miR‐32 was associated with larger tumour size (P = 0.012) and down‐regulated PHLPP2 was correlated with the advanced TNM stage (P = 0.002)." (PMID 31144439, 2019). "Besides that, high CXCL3 and ELF5 expression was also significantly related to vascular invasion, and low PHLPP2 expression was significantly associated with vascular invasion and tumor stage." (PMID 29209625, 2017). "Loss of function of PHLPP2 might result in tumorigenesis and tumor progression." (PMID 25823655, 2015). "Under hypoxic conditions in glioma, tumor exosome-derived miR-25-3p drives M2 polarization of TAMs by suppressing PHLPP2 and activating the PI3K/AKT/mTOR pathway, accelerating tumor progression." (PMID 41459510, 2025). "This PH domain is also present in the human PHLPP1 and PHLPP2 phosphatases, which are involved in apoptosis and the suppression of tumour growth." (PMID 38462784, 2024). "Analyses of these databases revealed that TRIM22 expression was downregulated in both total and paired HCC tumor tissues compared to normal tissues, while PHLPP2 expression was upregulated in HCC tumor tissues." (PMID 38199981, 2024). "Our data indicated that TRIM22 functions as a tumor suppressor by directly regulating the level of PHLPP2." (PMID 38199981, 2024). "LINC00461′s expression in CRC is inconsistent; some studies show that its upregulation promotes tumor growth and proliferation via the miR-323b-3p/NFIB axis, while others suggest that it downregulates tumor progression via miR-141/PHLPP2." (PMID 37760852, 2023). "The PHLPP2 gene was downregulated in the tumor samples, and its high expression level was correlated with a higher survival ratio in patients with READ." (PMID 37737218, 2023). "GSCs transfected with oe-SNAI2 + oe-PHLPP2 led to marked reduction in tumor weight and volume relative to oe-SNAI2 and increased tumor weight and volume relative to oe-PHLPP2 in nude mice xenografted with tumor." (PMID 35654777, 2022). "The pleckstrin homology domain leucine-rich repeat protein phosphatase 2 (PHLPP2), a tumor suppressor gene, can upregulate PHLPP2 from the PHLPP2-AKT-mammalian sterile 20-like kinase 1 (MST1) axis, exerting anti-proliferative effects." (PMID 35153781, 2022). "Taken together, our findings, for the first time, demonstrated that PHLPP2 acts as a tumor suppressor gene in CRC by restraining the Nrf2-ARE signaling pathway and increasing ROS levels, thus affecting the stemness of CRC cells." (PMID 35281874, 2022). "GSCs transfected with oe-SNAI2 + oe-PHLPP2 led to notably decreased p-Akt level relative to oe-SNAI2 and increased p-Akt level relative to oe-PHLPP2 in nude mice xenografted with tumor." (PMID 35654777, 2022). "Correlation with clinical data revealed that expression of PHLPP2 was negatively correlated with age, lymph node metastasis, lymph node positive ratio, tumor differentiation and TNM stage." (PMID 35281874, 2022). "Pleckstrin homology (PH) domain leucine-rich repeat protein phosphatase 2 (PHLPP2) is a critical regulator of cellular homeostasis and acts as a tumor suppressor in multiple human cancers." (PMID 35281874, 2022).